LEP (leptin)
Diseases named in the same sentence as LEP in open-access papers (continued):
Sharing a sentence is not in itself a finding about the gene and the disease.
Obesity (continued). "SOCS3 is a key regulator of IFN-I as well as of leptin and pro-inflammatory cytokines, which are elevated in obesity." (PMID 33430520, 2021). "Our aim was to investigate the regulation and molecular mechanism of the leptin signaling pathway in obesity-related OA." (PMID 34457118, 2021). "We observed that wheel-running training improved some endocrine features related to obesity, i.e., the serum levels of glucose and leptin." (PMID 34959794, 2021). "Infection with H. pylori leads to lower levels of ghrelin and leptin compared to those in other healthy people of the community, which in turn increases obesity and metabolic syndrome." (PMID 34922625, 2021). "Stratifying the analyses according to the presence of obesity and patients’ gender, differences were found for leptin (p = 0.0020 in women, p = 0.0055 in men) and leptin/ghrelin ratio (p = 0.048 in women, p = 0.004 in men)." (PMID 34829886, 2021). "The secretion of leptin is significantly increased from the obesity modified adipose stem cells (obASC) that further promotes EMT in cancer cells, paving a way towards cancer metastasis." (PMID 34588926, 2021). "Circulating leptin levels are elevated along with increased adipose tissue mass under conditions of obesity; however, like insulin resistance, leptin resistance aggravates metabolic disease due to inadequate appetite and metabolic control." (PMID 33924316, 2021). "As a consequence of obesity, the levels of adiponectin, a marker of insulin sensitivity, were decreased, while leptin, as expected, was increased in the obese mice." (PMID 35008488, 2021). "A shift toward the Th2-type immune response in airways is characteristic for the pathogenesis of asthma, thus providing a relevant link between obesity-induced high circulating leptin levels and the development of asthma." (PMID 34211985, 2021). "Our study aimed to evaluate the associations between the MC4R rs17782313, LEP rs7799039, and LEPR rs1137101 polymorphisms with obesity-related parameters in childhood and adulthood." (PMID 34205732, 2021). "Several mechanisms, including phosphorylation of Tyr985 in Ob-Rb and increased expression of SOCS-3, attenuate leptin signaling and promote a cellular resistance to leptin in obesity, which predominantly take place in the arcuate nucleus." (PMID 34209386, 2021). "The aim of this work is to extend our knowledge on the relationship between adipokine (leptin, ghrelin) and their ratio enforced by body mass index, obesity, diabetes, and metabolic syndrome." (PMID 34829886, 2021). "This review systematically discusses the interplay mechanism between leptin and inflammatory cytokines and their contribution to the fatal outcomes in COVID-19 patients with obesity." (PMID 34220807, 2021). "The increased leptin naive height-SDS in our patients is in line to observations in children with simple obesity." (PMID 34002033, 2021). "In contrast to leptin, circulating concentrations of adiponectin are low in patients who are affected by obesity, partly because of the presence of a feedback inhibition process." (PMID 33557015, 2021). "Significant alterations in chronic inflammation, particularly driven by persistent innate cytokine responses from adipocytes including IL-6, TNF-α, Type 1 IFN, and Leptin (modified from Alarcon, 2021), have been noted in the setting of obesity." (PMID 34835041, 2021). "In rats, the effects of leptin on ventilation are blunted with the increase in leptin levels induced by high-fat diet, suggesting a compromised ventilatory adaptation possibly induced by the development of leptin resistance in obesity." (PMID 34276408, 2021). "A more comprehensive anthropometric and clinical data is recommended for future studies to assess other obesity-related parameters (e.g., waist circumference, leptin levels)." (PMID 34743743, 2021).
Obesity (continued). "Sensitization to the adipokine leptin is a promising therapeutic strategy against obesity and its comorbidities and has been proposed to contribute to the lasting metabolic benefits of Roux-en-Y gastric bypass (RYGB) surgery." (PMID 34064308, 2021). "Some adipokines such as leptin or resistin are produced in excess in obesity while others, such as adiponectin, are reduced." (PMID 33418879, 2021). "When obesity occurs during the pregnancy, a resistance to leptin is observed with a decreased availability of nutrients for the fetus." (PMID 34652617, 2021). "Obesity promotes a low grade inflammation driven by many different cytokines and adipokines, including leptin, which has a key role in many other diseases due to its pleiotropic effects." (PMID 34827640, 2021). "Third, many studies have shown that the polymorphism in LEPR is associated with the levels of blood glucose, insulin, leptin, and triglyceride, and LEPR deficiency can directly lead to the accumulation of fat, resulting in obesity." (PMID 34419151, 2021). "The abundance levels of free fatty acids and of adipose tissue derived hormones, such as adiponectin and leptin are also altered in obesity and in the MetS." (PMID 33725017, 2021). "Adiponectin, along with leptin, is a major biomarker identified in obesity studies, and it is known to regulate appetite and help with insulin resistance." (PMID 34564426, 2021). "The increased plasma leptin with obesity has been related to changes in the brain RAS and the activity of the sympathetic nervous system, which determine the development of hypertension and metabolic alterations." (PMID 33572630, 2021). "Leptin also promotes the development of a variety of obesity related tumors, such as pancreatic cancer, ovarian cancer and colon cancer." (PMID 34485124, 2021). "It has been demonstrated that the high consumption of sugar and saturated fat induces an inflammatory response in the hypothalamus, in turn promoting the development of central leptin resistance and obesity." (PMID 34208585, 2021). "We demonstrated that RYGB surgery restores leptin's anorexigenic action via amelioration of hypothalamic inflammation and ER stress in diet-induced obesity." (PMID 33741533, 2021). "Fasting reduces circulating leptin levels, while eating or obesity increases leptin levels, which is consistent with our results." (PMID 34552154, 2021). "In parallel with increased visceral adiposity, the rise in circulating leptin and resistin levels exacerbates the local inflammation of adipose tissues, leading to obesity-related insulin resistance." (PMID 34579036, 2021). "Leptin is an important regulator of basal metabolism and food intake, with a pivotal role in obesity." (PMID 34202969, 2021). "Several mechanisms have been reported as link between CAN and obesity and insulin resistance, with a special focus on the role of leptin in modulating the energy expenditure and the sympathetic activity." (PMID 34827650, 2021). "Obesogenic diets alter the hypothalamic NPY expression, and elevated levels of NPY gene expression are found in several models of animal obesity such as diet-induced obesity (DIO), leptin deficient ob/ob mice and Zucker fatty fa/fa rats." (PMID 34445453, 2021). "Often this leads to obesity, which reduces the effectiveness of using exogenous leptin as a therapeutic agent." (PMID 34084149, 2021). "Another mechanism by which obesity distresses the liver is by adipocytes-derived adipokines, such as adiponectin and leptin, which lose their homeostasis in obesity." (PMID 34836382, 2021). "Further studies are needed to elucidate the role of leptin in the changes in neural transduction of sweet taste in obesity." (PMID 34960026, 2021). "It has been shown that probiotics can reduce leptin secretion and improve hypothalamic leptin and insulin resistance in high fat diet-induced obesity models in rodents." (PMID 34795562, 2021).
Obesity (continued). "Subsequently, MSG consumption leads to disruption of energy balance and disturbs the leptin-mediated hypothalamus signaling pathway, leading to obesity." (PMID 34026558, 2021). "Verrucomicrobia, along with its lower taxa levels, including Akkermansia, negatively correlated with body weight, fat mass, and leptin, suggesting Akkermansia as a microbial mediator of E2-dependent protection against obesity." (PMID 34436440, 2021). "New Zealand obese (NZO) mice, a model of polygenic obesity, have high levels of circulating leptin and hypertension, and are prone to develop SDB, similarly to human obesity." (PMID 34276408, 2021). "Together with our mouse data, these results suggest that Kdm6a inhibition sensitizes leptin signaling to reduce obesity‐related properties." (PMID 34306972, 2021). "The overexpression of leptin in obese patients can promote the development of obesity related triple negative breast cancer (TNBC) by promoting the accumulation of tumors stem cells (CSCs) and EMT." (PMID 34485124, 2021). "In accordance, the biological HSI > 36, reflecting NAFLD, was observed in 43.1% of patients (22/51) and leptin, produced by fat cells, was increased in blood of patients with obesity (p = 0.012)." (PMID 34038475, 2021). "GA-02 plays a role in obesity treatment by re-activating leptin signaling and reducing systemic and, more importantly, hypothalamic inflammation." (PMID 34526895, 2021). "Circulating leptin concentrations are closely correlated with the total amount of fat mass being, therefore, elevated in individuals with obesity." (PMID 33917063, 2021). "While the blood level of leptin increases in obesity-related hypertension, the blood level of ghrelin decreases." (PMID 33761942, 2021). "Leptin resistance can lead to obesity, but some drugs called leptin sensitizers can restore leptin sensitivity and produce a loss of body weight." (PMID 34066399, 2021). "A cooperative exchange of ghrelin and mediators associated with it, such as insulin, leptin, GIP, GLP-1, glucagon, and PAI-1, was revealed, which realizes their effects on obesity." (PMID 33959145, 2021). "Data from human as well as animal studies suggest that leptin plays a major role in the neurohormonal mechanisms of obesity-induced hypertension." (PMID 34966295, 2021). "In this study, obesity was induced by utilizing 60 kcal% high-fat feeding, and the role of leptin in lung tumorigenesis was elucidated by conducting in vivo and in vitro experiments." (PMID 33708630, 2021). "More over studies indicated that appetite-regulating hormones such as reducing leptin secretion and increasing ghrelin levels would be influenced by circadian rhythm disorders that can stimulate the appetite and food intake and induce obesity incidence." (PMID 33648476, 2021). "LDL correlated with PWV, TG with disease activity, PON activity with age, ARE activity with age and CV history, leptin with obesity and IMT." (PMID 34680168, 2021). "An increase in circulating plasma leptin is a typical characteristic of obesity and correlates with a leptin-resistant state." (PMID 34220807, 2021). "We next analyzed two genetic models of obesity: leptin gene mutant (ob/ob) mice and leptin receptor mutant (db/db) mice." (PMID 35011234, 2021). "In relation to obesity, the adipokine leptin can induce cell migration and invasion of breast cancer cells in a FAK-Src-STAT3 dependent manner." (PMID 33738261, 2021). "The critical role of the leptin-melanocortin system in the long-term sensing of body fat stores was first established in the 1990s, with defects in this system resulting in obesity in rodents and humans." (PMID 34045736, 2021). "Despite some reports linking LEP, obesity and OC, the molecular mechanism behind it is still poorly understood." (PMID 34884678, 2021). "Serum leptin concentrations correlate positively with the percentage of body fat, illustrating the insensitivity of most people suffering from obesity, to endogenous leptin production." (PMID 33866464, 2021).
Obesity (continued). "Obesity in CAH patients has been associated with glucocorticoid therapy, high androgen levels, leptin resistance, and decreased lipolysis due to the reduction in catecholamine secretion." (PMID 33486914, 2021). "Leptin concentrations are markedly increased in obesity, including fructose feeding model, and positively correlated with adipose mass, indicating leptin resistance." (PMID 34069933, 2021). "Obesity is characterized by elevated leptin levels, as well as by resistance to the anorectic effects of leptin." (PMID 33418879, 2021). "The stimulation of the HPT axis observed in obesity is mainly due to centrally acting leptin, which regulates the activity of neurons in the hypothalamus and has both direct and indirect effects on TRH–TSH secretion." (PMID 34574358, 2021). "Over the last decades, the discovery of leptin and its receptors and their relationship with obesity and inflammation has led the possibility of new research avenues to help better understand the behavior of many diseases, including cancer." (PMID 34202969, 2021). "The reason is that obesity enhances insulin resistance, while increased leptin or adiponectin prevents fat accumulation." (PMID 34221795, 2021). "‘Leptin resistance’ (a decrease in sensitivity to circulating leptin) often occurs in people with obesity and would negate the relationship between leptin and appetite." (PMID 34684403, 2021). "The concept of leptin resistance (LR) is important to the understanding of obesity in humans as well as in the diet-induced obesity (DIO) Western and db/db models." (PMID 34063911, 2021). "The hormone leptin negatively interferes with periodontal ligament cells’ regenerative capacity, suggesting leptin as a pathomechanical link between obesity and impaired periodontal healing." (PMID 34064286, 2021). "Both adipose associated immune cells (e.g., macrophages) and adipocytes release pro-inflammatory cytokines and adipokines, with obesity leading to increased serum leptin, increased serum resistin, and reduced serum adiponectin." (PMID 34777390, 2021). "Since its discovery, leptin has been considered as a possible alternative for the treatment of obesity due to its ability to stimulate lipolysis and raising body temperature." (PMID 35052534, 2021). "A high salt intake activates the aldose reductase–fructokinase pathway in the liver and hypothalamus, leading to leptin resistance and endogenous fructose production, which affects obesity, insulin resistance, and fatty liver disease." (PMID 34769575, 2021). "Genetic ablation of Rap1-GTPase shields against dietary obesity and imbalance of glucose, insulin, and leptin sensitivity, reduction in inflammation, and ER stress in the hypothalamus." (PMID 33669862, 2021). "Leptin is produced by adipocytes and hyperleptinemia is observed during obesity in parallel to central resistance to its anorexigenic action." (PMID 33816341, 2021). "First, researchers surmise that, similar to hyperleptinemia in patients with obesity and metabolic syndrome, leptin resistance is present in patients with OSAS." (PMID 34671315, 2021). "In this study, we investigate the molecular basis by which obesity and leptin signaling mediates CD4+ T cell expansion and effector responses in vitro." (PMID 35111163, 2021). "Obesity and myeloma share signaling pathways that upregulate insulin, IGF-1, leptin, and inflammatory cytokines, raising the risk of malignant transformation." (PMID 33531904, 2021). "Nevertheless, in obesity, increased fat mass is accompanied by hyperleptimenia, suggesting a state of leptin resistance." (PMID 34202323, 2021). "In our studies, both animal models—LD sheep as a physiological example of leptin resistance and sheep with high BW and high adiposity resulting from diet-induced obesity—demonstrated high leptin concentrations." (PMID 34438908, 2021). "In humans, plasma adiponectin concentrations decrease with obesity, and plasma leptin concentrations are highly correlated with BMI." (PMID 34575649, 2021).
Obesity (continued). "Given their high percentage of total body fat, individuals suffering from obesity show elevated leptin concentrations, a condition also referred to as hyperleptinemia." (PMID 33920604, 2021). "Similar to leptin and visfatin, other adipokines overexpressed in obesity, such as resistin, apelin, and chemerin, also possess some oncogenic functions." (PMID 33535537, 2021). "Leptin-stimulated sympathetic outflow to cardiovascular organs, however, remains intact in obesity, suggesting a phenomenon of selective leptin resistance." (PMID 34208939, 2021). "Generally, for all SLE patients, HC and the ‘SLE subgroup’ we observed a positive and mostly significant correlation of obesity (BMI) with leptin and CRP, in HC and the ‘SLE subgroup’ additionally between BMI and LPS levels." (PMID 34335609, 2021). "UCP3 is another homologous protein to UCP1 and exerts its anti-obesity action by regulating the level of leptin, thyroid hormones and β-adrenergic agonists." (PMID 34071722, 2021). "Leptin is a mediator of cardiac alteration in obesity, specifically can exert pro-fibrotic and pro-oxidant effects through the activation of PI3k-Akt signaling pathway, and subsequently the activation of TGF-β and connective tissue growth factor (CTGF)." (PMID 33809061, 2021). "Exposure during animal adulthood has been found to induce obesity, in part because of less energy expenditure (due to hypothalamic leptin resistance)." (PMID 33652701, 2021). "The VMH-specific primary cilia KO (IFT88-KOSF-1) mice exhibited metabolic dysregulation linked to decreased sympathetic nervous activity (SNA) and central leptin resistance, which led to marked obesity." (PMID 34211092, 2021). "Obesity is associated with elevated levels of the adipokine leptin, and epidemiological studies demonstrate that PLWH with higher circulating leptin levels have increased CD4+ T cell reconstitution compared to those with lower leptin levels." (PMID 35111163, 2021). "Leptin directly affects osteoblasts and indirectly affects bone mineral density through the change of body weight, in which leptin levels are higher in obese people, and obesity is positively correlated with bone mineral density." (PMID 34717752, 2021). "Taken together, these notable findings suggest that long-term doxepin use accelerates obesity development through the inhibition of leptin signaling." (PMID 33809508, 2021). "Overall, the identification of leptin has provided a framework for studying the pathogenesis of obesity in the diabetic population." (PMID 34446063, 2021). "This is consistent with previous reports that obesity leads to increased prostaglandin e and leptin protein levels." (PMID 34646336, 2021). "About 25 years after the discovery of leptin, one comes to mind about the effectiveness of leptin and its use to treat many diseases, both leptin mimics as in obesity and leptin-blockers as in tumors." (PMID 35027962, 2021). "These secondary metabolites reduce obesity through modulation of different hormones such as leptin, ghrelin and insulin." (PMID 34071722, 2021). "This is due to the role of obesity causing a systemic state, increasing the release of both pro-inflammatory cytokines and adipokines (e.g., TNF-α, IL-6, and leptin)." (PMID 34827640, 2021). "During obesity, the adipocytes accumulate more lipids and secrete increased levels of proinflammatory adipokines (leptin and resistin) and reduced levels of anti-inflammatory adipokines (adiponectin)." (PMID 33917607, 2021). "Increased insulin and leptin resistance in obesity is manifested as a proportional rise in fasted and stimulated blood concentrations of both hormones as a function of increased body fat." (PMID 34836068, 2021). "Within the context of diet, the role of the hypothalamus in the pathogenesis of obesity, pointed out even before leptin discovery, would contribute to the regulation of energy balance signals." (PMID 33919006, 2021).